MTOR (mechanistic target of rapamycin kinase)
Diseases named in the same sentence as MTOR in open-access papers (continued):
Sharing a sentence is not in itself a finding about the gene and the disease.
tumor (continued). "The mTOR catalytic kinase inhibitors AZD8055 successfully inhibited tumour growth in Lkb1−/− NIC mouse breast tumour model." (PMID 26196184, 2015). "The dynamics of tumor cell bioenergetics under genotoxic stress conditions, especially the mTOR-mediated inhibition of glycolysis in tumor adaptive resistance needs to be further investigated." (PMID 25807077, 2015). "Recent studies have shown that a particular microRNA, miR-451, regulates downstream molecules including AMPK and mTOR to determine the balance between rapid proliferation and invasion in response to metabolic stress in the harsh tumor microenvironment." (PMID 25629604, 2015). "With HER2 serving to amplify the signal, HER2/HER3 heterodimers potently activate the PI3K-Akt-mTOR signaling pathway that promotes tumor cell survival, therapeutic resistance, and metastatic dissemination." (PMID 26571496, 2015). "In conclusion, metformin reduced tumor proliferation in a pre-operative window study in obese EC patients, with dramatic effects on inhibition of the mTOR pathway." (PMID 25417601, 2015). "The Ras and PI3K-AKT pathways are interconnected and converge on mTOR signaling to control tumor cell growth." (PMID 25644510, 2015). "We experimentally show that MEK inhibition inhibits but mTOR inhibition relatively preserves anti-tumor T-cell responses both via tetramer-based flow cytometry in MOC1 tumor tissue and in an in vitro T-cell proliferation and activation assay." (PMID 26506415, 2015). "Lastly, experimental therapy of using PI3K/mTOR inhibitor NVP-BEZ235 successfully reduced primary tumor growth and lung metastasis." (PMID 25909167, 2015). "Further studies are required to delineate the exact role of mTOR driven senescence under high energy or CR environments in the tumor cells." (PMID 25895126, 2015). "FBXW7 primarily exerts its tumor suppressor activity by ubiquitinating different oncoproteins including mTOR." (PMID 26575021, 2015). "In mouse immortalized cell lines, LDHB is critical in the mechanistic target of rapamycin (mTOR) pathway to induce tumor formation." (PMID 25652794, 2015). "The role of autophagy in tumor suppression can also be observed during the upregulation of members of the phosphatidylinositol 3-kinase (PI3K) family to similar levels as the MTOR and AKT kinases." (PMID 26284195, 2015). "mTOR pathways are often aberrantly activated in a wide variety of tumors, and the hyperactivated mTOR pathways contribute to tumor proliferation and survival." (PMID 26213847, 2015). "Rapamycin is an mTOR inhibitor and an antifungal agent with immunosuppressive properties, which has an established effect on suppressing tumor growth in a number of solid tumors." (PMID 26397134, 2015). "The benefit from mTOR inhibitors varies, likely as a consequence of tumour heterogeneity, and upregulation of several compensatory feed-back mechanisms." (PMID 26698305, 2015). "PI3K/AKT/mTOR signaling can increase HIF-1α activity by inducing its stabilization, and we and others have shown that melatonin regulates the PI3K/AKT/mTOR pathway in some tumor types." (PMID 26252771, 2015). "Activation of the PI3K/AKT/mTOR signaling pathway mediated through molecular aberrations is instrumental in promoting tumor development as well as resistance to anticancer therapies." (PMID 26421002, 2015). "There has been much debate, testing and intensive continuing research regarding the potential anti-tumour effects of mammalian target of rapamycin (mTOR) inhibitors." (PMID 25699174, 2015). "Hyperactivation of the mTOR pathway, leading to increased cell growth and proliferation, stimulates tumor growth in the brain and other organs in patients with TSC." (PMID 25574245, 2015). "It has been reported under nutrition starvation, AMPK was activated to suppress mTOR-dependent transcriptional regulators to keep tumor cell survival." (PMID 25792973, 2015).
tumor (continued). "Research on the mammalian target of rapamycin (mTOR) inhibitors rapamycin, everolimus, and temsirolimus have shown mTOR suppression and delayed tumor advancement." (PMID 26393639, 2015). "Studies have reached an agreement with the view that tumor cell proliferation is decreased if a lower level of mTOR is obtained." (PMID 25854175, 2015). "The liver kinase B1 (LKB1) and AMPKα/mTOR pathways play a central role in tumor cell survival in response to cellular stress." (PMID 26280348, 2015). "The quantitative analysis showed a decrease in PI3K/mTOR, survival and stemness signaling, but the pro-apoptosis and tumor suppressive molecules were up-regulated in ABT-263 treated cells." (PMID 26317542, 2015). "As a result, the inhibition of mTOR has been extensively tested as a therapeutic approach to target LKB1−/− tumour cells and mouse models of cancer." (PMID 26196184, 2015). "PTEN and PTPN14 have been shown to play crucial roles in cell proliferation and tumor growth by regulating mTOR and Hippo signaling pathways." (PMID 25803229, 2015). "PTEN promoter methylation correlates with decreased PTEN protein expression, which often increases AKT/mTOR pathway activation in tumor progression." (PMID 25762617, 2015). "In tumour biopsies, mTOR activation increased upon treatment with gemcitabine and returned to control levels upon fasting." (PMID 26176887, 2015). "It has been proven to mediate ubiquitin-dependent proteolysis of several well-known oncoproteins including Notch, cyclin E1 and mTOR, and regarded as a tumor suppressor at the crossroads of cell division, growth and differentiation." (PMID 25749036, 2015). "The multivariate analysis for immunohistochemical parameters adjusted by AJCC stage and tumor location indicated that the positivities for p-Akt, p-mTOR, p-S6RP and HSP90 were poor prognostic factors for OS." (PMID 26502919, 2015). "Inhibitors FH-535 (WNT/β-catenin), IWP-2 (WNT) and PI-103 (PI3K/mTOR) effectively eliminated tumor cells/organoids." (PMID 26375443, 2015). "Consistent with the results in vitro, the intensity and percentage of p-mTOR, pS6, and p4EBP1 staining of tumor sections was lower in the metformin treated group than in the untreated group." (PMID 25909163, 2015). "Aberrant activation of the PI3K/PTEN/AKT/mTOR signaling pathway is a common event in a wide range of tumor types, suggesting a role for this pathway in carcinogenesis." (PMID 25654238, 2015). "For example, these phospho (p)-proteins, except p-mTOR, were positively correlated with latency and lifespan, but were negatively related to metastasis and tumor numbers." (PMID 25853295, 2015). "Studies have indicated that phosphorylation of p70 S6 kinase and 4EBP1 by mTOR plays an essential role in tumor growth and metastasis." (PMID 26582057, 2015). "Mechanistic study revealed that RY-2f exerted the anti-tumor activities mainly through suppression of the PI3K/AKT/mTOR signaling." (PMID 26325371, 2015). "FAK determines tumor aggressiveness by both the induction of matrix MMPs (via PI3K/Akt/mTOR pathway) and EMT." (PMID 26210994, 2015). "To evaluate alterations in kinase levels following treatment with dasatinib, we measured expression of p-Lyn, p-PI3K, p-Akt, and p-mTOR in tumor tissues of the Jeko1/BTZ xenografted model." (PMID 26517678, 2015). "Third, mTOR overexpression was frequently observed in liver metastases compared with the primary tumor, and an inverse correlation was found between the expression levels of miR-99b-5p and mTOR in CRC patients with liver metastasis." (PMID 26259252, 2015). "Activation of a different prosurvival signaling pathway upon mTOR inhibition explains as to why the tumor shows an initial response followed by rapid progression." (PMID 25741318, 2015). "Functional enrichment analysis of putative and validated miRNA targets highlighted cellular processes such as tumor suppression, anti‐inflammatory response, and modulation of Wnt, insulin, mTOR, and MAPK signaling pathways, among others." (PMID 26176567, 2015).
tumor (continued). "Emerging preclinical evidence suggests that mTOR inhibition can potentiate the antitumor efficacy of conventional cytotoxic agents in multiple tumor types in vivo and in vitro." (PMID 24916546, 2014). "Of note, this is strengthened by xenograft experiments, where the rapamycin (mTOR inhibitor) treatment increases macroautophagy and SA-βGal positive staining, and delays tumor growth." (PMID 25324830, 2014). "We previously reported on the disappointing results of the combination of mTOR inhibitor RAD001 with 177Lu-DOTATATE PRRT in the CA20948 rat tumor model." (PMID 24995150, 2014). "The phosphoinositide 3-kinase (PI3K)/Akt/mammalian target of rapamycin (mTOR) signaling pathway is extremely important in the regulation of the cell cycle, tumor cell proliferation, apoptosis, tumor invasion, metastasis, angiogenesis and multidrug resistance." (PMID 24944709, 2014). "As the special inhibitors of mTOR, rapamycin and its anologs have been evaluated in many tumors including ESCC and have shown the marked inhibition effects on the mTOR pathway and tumor growth." (PMID 24818169, 2014). "Activation of the PI3K/Akt/mTOR signalling pathway can lead to increased cell proliferation and dysfunction of tumor suppression function." (PMID 24670368, 2014). "The phosphoinositide-3-kinase-Akt-mTOR pathway is a key mediator of cellular proliferation, apoptosis, migration, and angiogenesis - all critical to tumor aggressiveness." (PMID 25757219, 2014). "PTEN is a tumor suppressor gene that functions to antagonize the PI3K/AKT/mammalian target of rapamycin (mTOR) pathway." (PMID 25055199, 2014). "The phosphatidylinositide 3-kinase (PI3K)/AKT/mammalian target of rapamycin (mTOR) signaling pathway is a critical driver of tumor progression." (PMID 24387695, 2014). "More importantly, dysregulated NEDD4 degradation led to reduction in PTEN expression and subsequent hyper-activation of the oncogenic mTOR/Akt pathway, resulting in enhanced tumor cell proliferation and growth." (PMID 24657926, 2014). "Mammalian target of rapamycin (mTOR) inhibitors have osteoblast-stimulatory as well as osteoclast- and tumor-inhibitory actions." (PMID 25757219, 2014). "In contrast, several studies have shown that inhibition of mTOR sensitizes tumor cells to cisplatin, paclitaxel, and doxorubicin." (PMID 25232533, 2014). "For example, enhanced anti-tumor activity was reported by combining specific Akt and mTOR inhibitors." (PMID 24416349, 2014). "mTOR inhibitors work by affecting tumor cell growth, including growth, proliferation, survival, transcription, and protein synthesis." (PMID 25089218, 2014). "Mutations in PI3 kinase result in activation of the PI3 kinase/AKT/mTOR pathway and are present in various tumor types." (PMID 24742900, 2014). "We also analyzed the combination of bicalutamide +/- the pan-PI3K inhibitor GDC-0941 or the dual PI3K/mTOR inhibitor GDC-0980 in xenograft tumor studies and observed additive effects." (PMID 25103565, 2014). "Several miRNAs were shown to regulate mTOR in tumor cells, including miR-7, miR-99a, miR-100 and miR-101." (PMID 25141911, 2014). "In OS cells lines from dogs, mTOR and its downstream product have been shown to be present and active, and pathway inhibition by rapamycin decreased the survival rate of the tumor cells." (PMID 24765137, 2014). "The role of survivin in mediating the anti-tumor efficacy of IGFR/PI3K/Akt/mTOR vertical blockade was also examined." (PMID 24387108, 2014).
tumor (continued). "Activating the mTOR pathway by IGF induced distinct alterations of the histone acetylation level in DU-145 tumour cells." (PMID 24779401, 2014). "Compared to the non-tumor counterparts, the expression of mTOR protein was significantly increased in tumor tissues from ten different patients." (PMID 24637915, 2014). "It is intriguing that this same tumour subtype seems to express high levels of both mTOR and AMPK signalling pathways." (PMID 27919039, 2014). "Some of the products encoded by these genes represent the main target of new therapies aimed at inhibiting tumour growth acting mainly on angiogenesis and mTOR pathway." (PMID 25277184, 2014). "When tumors were dichotomized into small (<2 cm) and large (≥2 cm) size, the median H scores for mTOR were significantly higher in small versus large tumor size (median H score 225 versus 180, respectively, Mann–Whitney two tailed P = 0.012)." (PMID 24887419, 2014). "It has been suggested that tumour formation in PJS is associated with the downstream effects of the loss of LKB1 and the removal of inhibition of the mTOR pathway." (PMID 25190708, 2014). "In some malignancies, proteins lying downstream of the mTOR pathway have been also altered, for example, eIF4E, which promotes the phosphorylation of 4EBP1 (p-4EBP1), expression levels of which correlate with tumor progression." (PMID 24818169, 2014). "In cases where non-tumour urothelium, with apparent normal histology or hyperplasic samples were scored as positive (36%, 27/76), p-mTOR expression was completely restricted to the superficial cell layers, predominantly to the umbrella cells." (PMID 25202348, 2014). "Activation of AMPK regulates the growth of tumor cells through inhibition of the mammalian target of rapamycin (mTOR) pathway." (PMID 25310259, 2014). "Previous studies have shown that inhibitors of the mammalian target of rapamycin (mTOR) or the MAPK signaling pathways enhanced the anti-tumor effects of metformin." (PMID 25118792, 2014). "PCa is characterized by alterations in the PI3k/Akt/mTOR pathway and by a unique lipogenic reprogramming, active both at tumor initiation and in advanced stages." (PMID 24497570, 2014). "RAD001 has been reported to show anti-tumor and anti-angiogenic activity both in vitro as well as in vivo, since both tumor proliferation and tumor angiogenesis are regulated by mTOR." (PMID 24995150, 2014). "There is now extensive experience with everolimus in several tumor types, as well as experience with other mTOR inhibitors." (PMID 25420955, 2014). "Of the non-tumour and tumour sections, 36 and 20% were scored positive for p-mTOR expression, respectively." (PMID 25202348, 2014). "Previous studies showed that tumor cell lines with FBXW7 gene mutations are sensitive to rapamycin, suggesting a potential rationale for treating such tumors with mTOR inhibitors." (PMID 24586741, 2014). "As a central integrator of cell metabolism, growth, proliferation and survival, aberrant mTOR signaling participates in tumor autophagic responses to various stresses." (PMID 25115395, 2014). "In a subgroup analysis of ERα-positive and PgR-positive patients, Bostner and colleagues recently observed a reduced benefit from tamoxifen in those patients whose tumor expressed high p-mTOR." (PMID 24447434, 2014). "RAD001 is used clinically against a small selection of tumors, but mTOR inhibitors activate tumor survival pathways by complex feedback mechanisms." (PMID 25061503, 2014). "In the majority of MI tumour sections, immunoexpression was lost in a de novo fashion, as supported by the maintenance of p-mTOR expression in the normal-like adjacent mucosa." (PMID 25202348, 2014).
tumor (continued). "Targeting of mTOR with an mTOR inhibitor (rapamycin analog) has shown tumor growth inhibition in several PDAC cell lines." (PMID 24624093, 2014). "Other studies have shown that Gadd45a inhibits tumor angiogenesis via blocking of the mTOR/STAT3 pathway." (PMID 24658029, 2014). "We were therefore interested in understanding how mTOR inhibition affected tumours in KC PTEN mice at cellular level." (PMID 24717934, 2014). "It has been shown that inflammation-related factors can activate MTOR can promote tumor angiogenesis by phosphorylating TSC1 (also known as hamartin) and thereby inactivating the TSC1-TSC2 complex." (PMID 25541970, 2014). "Patients with lower levels of p-mTOR expression following NAC are likely to have smaller tumor sizes." (PMID 25364442, 2014). "Inactivation of the VHL gene also enhances tumor cell growth though the mammalian target of rapamycin (mTOR) pathway." (PMID 24568263, 2014). "Phospho-mTOR levels increased in conjunction with increased tumor burden in Akt1−/− and Akt3−/− mice, remained constant in Akt2−/− mice and tapered off in WT mice with late stage tumors." (PMID 24722238, 2014). "Sestrin 1 (SESN1), a putative tumor suppressor and mTOR signaling inhibitor, was identified as a gene synergistically up-regulated commonly in 3 of 4 EZH2 mutant cells with combination treatment, but not in EZH2 wild-type cells." (PMID 25493630, 2014). "Activation of PI3K/Akt/mTOR signaling contributes to the pathogenesis of many tumor types, and thus the pathway is being actively pursued as a promising therapeutic target." (PMID 25261369, 2014). "The mTOR inhibitor sirolimus, by inhibiting the activation of the mTOR pathway, has been found to be effective in preventing tumor growth and re-bleeding in patients with TSC." (PMID 24504542, 2014). "We first examined the effects of an mTOR inhibitor, RAD001 (everolimus), on cell proliferation, cell cycle, AKT/mTOR signaling, and xenograft tumor growth in EpS cell lines." (PMID 25098767, 2014). "Our data indicated that combining the IGFR inhibitor NVP-AEW541 with inhibitors against PI3K/Akt/mTOR pathway (MK2206 or BEZ235) results in synergistic anti-tumor effects in HCC cells in vitro and in vivo." (PMID 24387108, 2014). "Pathway interlinking in tumor formation is still not well understood, although recent evidence has described the role of mammalian target of rapamycin (mTOR) in linking different signaling pathways together in trichofollicular tumorigenesis." (PMID 24451143, 2014). "The same rational is true regarding the glucose uptake ability, since mTOR increases GLUT1 expression via HIF1α in some tumours, while AMPK pathway also leads to increased glucose uptake and hexokinase activity in normal thyrocytes." (PMID 27919039, 2014). "The expression of p-mTOR decreased with increasing stage: 40% (6/15) of pT1 and pTis tumours were positively stained, while only 14.3% (7/49) of pT3/pT4 tumours expressed p-mTOR (P=0.087)." (PMID 25202348, 2014). "To better evaluate a role for miR-155 expression with respect to mTOR signaling and the ERα gene signature, we next analyzed expression of the miR-155 host gene (miR-155HG) across TCGA tumor data." (PMID 25283550, 2014). "Combined treatment with RT and BKM120 suppressed levels of radiation-activated Akt and mTOR in tumor tissues." (PMID 25004403, 2014). "In fact, the immediate action on epigenetic molecules following mTOR suppression suggests that the anti-tumour potential of mTOR inhibitors is restricted per se, regardless of drug exposure time." (PMID 24779401, 2014). "Additional downstream targets for mTOR include p70S6kinase and eukaryotic initiation factor-4E (eIF-4E), which are involved in modulating tumor cell metabolism, apoptosis, and autophagy." (PMID 25140303, 2014).